IL17B (interleukin 17B)
Diseases named in the same sentence as IL17B in open-access papers (continued):
Sharing a sentence is not in itself a finding about the gene and the disease.
gastric cancer (11 papers, 2016 to 2023). A primary or metastatic malignant neoplasm involving the stomach. "In the following study, we confirmed gastric cancer cells cannot autocrine IL-17B, and showed that increased levels of IL-17RB were associated with poor prognosis in gastric cancer patients." (PMID 27146881, 2016). "In terms of function, high expression of IL-17B was mainly linked to poor prognosis in cancer; such as breast and gastric cancer Besides that, IL-17B could play a pathogenic role in the joint." (PMID 30127781, 2018). "In gastric cancer, the proliferation and migration of tumor cells can be promoted via the IL-17B/IL-17RB axis, which also upregulates cell stemness by triggering the AKT/β-catenin pathway." (PMID 37686343, 2023). "Others confirmed a direct tumor-promoting activity of IL-17B in gastric cancer, thyroid cancer, and in acute myeloid leukemia." (PMID 33244315, 2020). "Our data revealed a new mechanism that IL-17B enhanced the progression of gastric cancer by activating mesenchymal stem cells." (PMID 28145881, 2017). "Interleukin-17B acts in a paracrine fashion since it has also been detected locally in gastric cancer but only at low levels, whereas the expression of its receptor IL-17RB was increased and correlated with poor prognosis." (PMID 27589729, 2016). "The AKT inhibitor, LY294002, was used to characterize the IL-17B-activated AKT/β-catenin pathway in gastric cancer cells, and western blotting was used to measure the expression of β-catenin and stemness-related genes treated with or without exogenous rIL-17B." (PMID 27146881, 2016). "IL-17B/IL-17RB signaling promoted the upregulation of stemness and EMT formation in gastric cancer cells treated with exogenous recombinant human IL-17B (rIL-17B) by the AKT/β-catenin pathway." (PMID 27146881, 2016). "Evaluation of the IL-17B/17-RB axis in gastric cancer cells, reported that it promoted proliferation and migration as well as stemness phenotype as assessed by the detection of stem cells markers Oct4, Nanog, Lgr5, Sall4." (PMID 27589729, 2016). "To characterize the role of IL-17B/IL-17RB signaling on the stemness of gastric cancer, we performed real-time quantitative PCR to examine the expression of Oct4, Nanog, Lgr5, and Sall4 mRNA in MGC-803 cells treated with exogenous rIL-17B." (PMID 27146881, 2016). "To further confirm that the amplified IL-17RB functions in gastric cancer tissues need paracrine IL-17B, we depleted IL-17RB using its corresponding shRNA." (PMID 27146881, 2016). "Overall, these findings suggest that exogenous IL-17B combined with IL-17RB contributes to the proliferation and migration of gastric cancers." (PMID 27146881, 2016). "AKT/GSK-3β/β-catenin signaling pathway was promoted by IL-17B/IL-17RB signaling pathway to up-regulate Sox2, Oct4 and Nanog proteins, inducing stem cell transformation and epithelial to mesenchymal transformation of gastric cancer and lung cancer cells." (PMID 35392087, 2022). "In total, IL-17B also could indirectly promote gastric cancer progression by influencing the biological behavior and function of hucMSCs and GC-MSCs." (PMID 28145881, 2017). "We have previously demonstrated that IL-17B/IL-17RB signal promoted progression of gastric cancer." (PMID 28145881, 2017). "The results showed that the expression of IL-17B in gastric cancer tissues decreased." (PMID 27146881, 2016). "We hypothesize that IL-17B/IL-17RB signaling enhances the stemness of gastric cancer by the AKT/β-catenin pathway." (PMID 27146881, 2016). "We postulate that amplified IL-17RB in gastric cancer tissues may depend on IL-17B derived from the tumor microenvironment." (PMID 27146881, 2016). "To elucidate how IL-17B/IL-17RB signaling promotes gastric cancer stemness and EMT, we analyzed the expression of proteins that could bind to the SEFIR domain within the cytoplasmic tails of IL-17RB." (PMID 27146881, 2016).
gastric cancer (continued). "To further substantiate that IL-17B/IL-17RB signaling was essential in promoting upregulation of stemness-related genes in gastric cancer, we compared the protein expression by western blotting between IL-17RB-shRNA-MGC-803 cells and control cells treated with exogenous rIL-17B." (PMID 27146881, 2016). "Therefore, identifying potential cellular sources of IL-17B is crucial for searching for a promising therapeutic target to inhibit gastric cancer progression in future studies." (PMID 27146881, 2016). "Together, the results suggest that IL-17B/IL-17RB signal may induce stemness in gastric cancer cells by activating the AKT/β-catenin pathway." (PMID 27146881, 2016). "Moreover, a relationship between IL-17B and stemness has been found in gastric cancer." (PMID 33244315, 2020). "Our previous results also indicated that the IL-17B/IL-17RB signal can activate the AKT/β-catenin pathway in gastric cancer.To elucidate how IL-17B promotes MSCs stemness, proliferation and migration, we analyzed the expression of proteins that could be activated by IL-17 family cytokines." (PMID 28145881, 2017). "However, the role of IL-17B/IL-17RB (IL-17 receptor B) signaling to stemness of gastric cancer remains unknown." (PMID 27146881, 2016). "IL-17B activates the AKT/β-catenin pathway and promotes stemness and EMT of MGC-803 human gastric cancer cells." (PMID 32373132, 2020). "To further confirm the role of IL-17B/IL-17RB signaling in gastric cancer, we performed colony forming assays and Transwell® assays using IL-17RB-depleted MGC-803 cells by adding exogenous recombinant human IL-17B (rIL-17B) protein." (PMID 27146881, 2016). "Because the ligands of IL-17RB were IL-17B and IL-17E/IL-25, we quantitated the expressions of IL-17B and IL-17E mRNA in gastric cancer tissues and matched non-cancerous tissues by real-time quantitative PCR." (PMID 27146881, 2016). "Indeed, Bie and colleagues showed that mesenchymal stem cells (MSCs) produce IL-6, IL-8, TGF-β, and CCL-5 following IL-17B stimulation and that supernatants collected from MSCs incubated with recombinant IL-17B promote the proliferation of MGC-803 gastric cancer cells in vitro." (PMID 32373132, 2020). "Moreover, RT–PCR analyses showed no detectable IL-17B expression in gastric cancer cell lines, we excluded these cells autocrine IL-17B." (PMID 27146881, 2016). "Together, our results indicate that the IL-17B/IL-17RB signal can promote the growth and migration of tumor cells, and upregulate cell stemness through activating the AKT/β-catenin pathway in gastric cancer, suggesting that IL-17RB may be a novel target in human gastric cancer therapy." (PMID 27146881, 2016).
pulmonary fibrosis (10 papers, 2019 to 2024). Chronic progressive interstitial lung disorder characterized by the replacement of the lung tissue by connective tissue, leading to progressive dyspnea, respiratory failure, or right heart failure. "Current studies indicate that IL-17B is associated with the occurrence and progression of pulmonary fibrosis and systemic sclerosis." (PMID 39502194, 2024). "Additionally, in a mouse model of bleomycin-induced pulmonary fibrosis, IL-17B deficiency has been shown to slow the progression of fibrosis." (PMID 39502194, 2024). "Another study demonstrated that Actinomyces and Prevotella promote pulmonary fibrosis in mice through IL-17B signaling." (PMID 39233908, 2024). "Accordingly, pre-clinical evidence suggests that Prevotella predominance in the airways promotes pulmonary fibrosis through a mechanism involving interleukin-17B." (PMID 37228285, 2023). "Currently, Studies have revealed that IL-17A, IL-17B, and IL-17E are all involved in the development and promotion of pulmonary fibrosis." (PMID 37858084, 2023). "IL17B has been reported to have a proinflammatory activity similar to IL25 in lung fibrosis and eliciting type 2 cytokine responses." (PMID 36814913, 2023). "Recently, it was reported that IL-17B, which (like IL-25) is a ligand for IL-17RB, is crucial for development of bleomycin-induced pulmonary fibrosis in mice by promoting type 3 immune responses in mice." (PMID 31745167, 2019). "In addition, murine model of bleomycin-induced lung fibrosis has found that dysregulated lung microbiota can promote the production of interleukin-17B (IL-17B), driving disease progression." (PMID 39760094, 2024). "Also a dysregulated lung microbiota can drive IL-17B production, as it has been shown in a mouse model of bleomycin-induced lung fibrosis." (PMID 33244315, 2020). "IL-17A and IL-17B have also been found in the bronchoalveolar lavage fluid of patients affected by lung fibrosis, but antibiotic treatments did not appear to be beneficial in limiting acute exacerbation in these patients." (PMID 33244315, 2020).
colitis (8 papers, 2017 to 2024). Inflammation of the colon. "In this study, we used single cell RNA sequencing (scRNAseq) to reveal that IL17B deficiency led to an altered immune cell landscape in DSS-induced colitis mouse model." (PMID 36814913, 2023). "The loss of IL17B in mice caused more severe DSS-induced colitis than WT mice and reconstitution of IL17B in Il17b-/- mice alleviated severity of colitis." (PMID 36814913, 2023). "IL17B deficiency resulted in severe DSS-induced colitis with exaggerated weight loss, shorter colon length, and elevated proinflammatory cytokines in colon." (PMID 36814913, 2023). "Single cell transcriptional analyses of CD45+ immune cells in colonic lamina propria revealed that loss of IL17B resulted in an increased neutrophil infiltration and enhanced inflammatory cytokines in intestinal macrophages in colitis, which were confirmed by real-time PCR and flow cytometry." (PMID 36814913, 2023). "Interestingly, although IL-17B and IL-17E (IL-25) share a common receptor, IL-17RB, IL-17B, and IL-17E deficiency lead to opposite results in a model of acute colitis induced by dextran sulfate sodium." (PMID 32373132, 2020). "One of the few existing studies suggested that IL-17B regulates the response of colonic myeloid cells to inhibit colitis, which is the same as the results of this study." (PMID 38698841, 2024). "Comparing the cell composition of colitis in Il17b-/- and WT mice revealed neutrophils were significantly increased and macrophages presented a proinflammatory status in colon tissue." (PMID 36814913, 2023). "The results showed an obvious increase of cell percentage of cluster 4 (myeloid cells) and a decrease of cluster 7 of myeloid cells in Il17b-/- colitis mice compared to WT colitis mice and the trend was similar in two separate samples in each group." (PMID 36814913, 2023). "First, we treated Il17b-/- colitis mice with recombinant mouse IL17B and detected cell response in colon with flow cytometry and found that IL17B treatment can inhibit S100a9+ neutrophils infiltration in colon tissue." (PMID 36814913, 2023). "In this study, we use scRNAseq to reveal that IL17B can exert its inhibitory role by regulating colon myeloid cell function in colitis, which is a new mechanism of IL17B function in colitis." (PMID 36814913, 2023). "Reconstitution of Il17b-/- mice with recombinant IL17B alleviated the severity of DSS-induced colitis." (PMID 36814913, 2023). "The expression of S100a9, S100a8, Lcn2, Il1f9, Mmp8, and Mmp9 were significantly increased in CD45+ cells from Il17b-/- colitis mice (P < 0.05)." (PMID 36814913, 2023). "To avoid bath effects, we stained cells from each mouse of 2 WT and 2 Il17b-/- colitis mice with sample tags and pooled them together for downstream process using BD Rhapsody system." (PMID 36814913, 2023). "TNF, IL1B, and IL6 were increased in Il17b-/- mice compared with WT in colitis in both protein and mRNA levels." (PMID 36814913, 2023). "ScRNAseq analysis of CD45+ immune cells from colonic lamina propria of 2 WT and 2 Il17b-/- mice with colitis revealed the infiltration of myeloid cell, T cells, B cells, and plasma cells." (PMID 36814913, 2023). "The expression of Il1a, Ccl5, Il1b, Ccl3, and Cxcl1 were significantly elevated in CD45+ cells from Il17b-/- colitis mice (P < 0.05)." (PMID 36814913, 2023). "IL17B exerts its protective role on colitis by inhibiting neutrophils infiltration, and suppressing proinflammatory cytokines production in intestinal macrophages in colon." (PMID 36814913, 2023). "Here, we aimed to illustrate the IL17B dependent cellular and molecular changes in colon tissue in a mouse colitis model." (PMID 36814913, 2023). "Among these, the role of IL17A, IL17F, IL17C, and IL17E in colitis and their mechanisms have been thoroughly investigated, whereas IL17B is less studied." (PMID 36814913, 2023). "Previous study shows that IL17B can compete with IL25 for binding IL17RB to inhibit the pathologic role of IL25 in colitis." (PMID 36814913, 2023).
colitis (continued). "H-E staining of the colon tissues showed greater inflammatory cells infiltration and epithelial cells destruction in Il17b-/- colitis mice.We measured the levels of the inflammatory cytokines in colon homogenates at day 8 of colitis." (PMID 36814913, 2023). "Whereas resident macrophage marker C1qb and C1qc were reduced in CD45+ cells from Il17b-/- colitis mice (P < 0.05)." (PMID 36814913, 2023). "Increased accumulation of CD11B+Ly6G+S100A9+ neutrophils in colon lamina propria in Il17b-/- colitis mice were validated by flow cytometry." (PMID 36814913, 2023). "We used scRNAseq to analyze colonic lamina propria immune response in colitis with an unbiased pattern, which provides a comprehensive view of immune response regulated by IL17B and avoids the limitation of studying a specific cell population." (PMID 36814913, 2023). "Consistent with this study, our results also confirm the protective role of IL17B in colitis model using a different deletion system." (PMID 36814913, 2023). "Overall, we defined a new function of IL17B by regulating intestinal macrophages and recruiting neutrophils in colitis." (PMID 36814913, 2023). "The protective role of IL17B in colitis is assumed to competitively inhibit IL25-driven colon inflammation." (PMID 36814913, 2023). "On other hand, it has been reported that IL17B exhibits a suppressive role in colitis and Citrobacter rodentium infection." (PMID 36814913, 2023). "Further we sorted CD45+ immune cells from mouse colonic lamina propria on day 8 after colitis induction and performed single cell RNA sequencing (scRNAseq) to find out the effect of IL17B on colonic immune response in colitis." (PMID 36814913, 2023). "However, we did observe higher expression of key inflammatory cytokines (Il6, Il1b, Il17b) and chemokines (Cxcl1 and Cxcl2) involved in colitis in wild-type compared to R38E-PAR2 mice." (PMID 39171684, 2024). "Thus, IL17B deficiency results in increased neutrophils infiltration in response to colitis, which is a new function of IL17B." (PMID 36814913, 2023). "However, the deficiency in IL-25 was protective against dextran sulfate sodium (DSS)-induced colitis and a defective expression of IL-17B exacerbated the development of acute colitis." (PMID 37005677, 2023). "To further confirm the protective role of IL17B in colitis, we treated Il17b-/- mice with recombinant mouse IL17B to see if it could reduce the colitis severity." (PMID 36814913, 2023). "IL17B is a novel inhibitory cytokine which could be potentially serve as biomarkers and protective new targets harnessed for colitis therapy." (PMID 36814913, 2023). "IL17B inhibits colitis by regulating colonic myeloid cell response." (PMID 36814913, 2023). "IL17B expression in mouse colitis model has been reported, but its expression in IBD patients is still unknown." (PMID 36814913, 2023). "Injection of recombinant IL17B can reduce colitis severity, suggesting that IL17B is another novel anti-inflammatory cytokines, which might have the therapeutic potential for IBD patients." (PMID 36814913, 2023). "In this study, we focus on the effect of IL17B on immune cell responses in colitis model." (PMID 36814913, 2023). "Furthermore, the IL-17B deficiency was found to be pathogenic for Citrobacter rodentium infection, which resembled DSS-induced colitis, whereas Il25−/− mice were protected against Citrobacter rodentium infection." (PMID 37005677, 2023). "IL17B is reported to be protective in dextran sulfate sodium (DSS)-induced colitis mice model, since deficiency of IL17B results in increased susceptibility to colonic inflammation." (PMID 36814913, 2023). "However, IL-17B and IL-25 appear to have opposite functions in colon inflammation." (PMID 38068860, 2023). "However, whether there are other mechanisms of IL17B function in colitis is still unknown." (PMID 36814913, 2023).
colitis (continued). "To explore the mechanisms of IL17B in the development of colitis, we created a mouse strain with a targeted deletion of exon 2 of IL17B by CRISPR/Cas-mediated genome engineering and confirmed the deletion of IL17B gene." (PMID 36814913, 2023). "In colitis, CD11B+S100A9+ neutrophils were significantly increased in WT mice compared to mice without DSS treatment, and this population was 2-fold increase in Il17b-/- colitic mice." (PMID 36814913, 2023). "We then induced the colitis with DSS in WT and Il17b-/- mice." (PMID 36814913, 2023).
psoriasis (8 papers, 2017 to 2025). An autoimmune condition characterized by red, well-delineated plaques with silvery scales that are usually on the extensor surfaces and scalp. "Compared to IL-17A, IL-17F, and IL-17A/F heterodimers, IL-17B, IL 17C, IL-17D, and IL-17E are less characterized in the context of psoriasis." (PMID 40243580, 2025). "Subsequently, we will summarize the current knowledge around IL-17A and its five currently known homologues, namely IL-17B, IL-17C, IL-17D, IL-17E (also known as IL-25) and IL-17F, in relation to psoriasis with a focus on the most recent discoveries." (PMID 37283755, 2023). "In this review, we will summarize the current knowledge around IL-17A and its five currently known homologues, namely IL-17B, IL-17C, IL-17D, IL-17E (also known as IL-25) and IL-17F, in relation to skin inflammation in general and psoriasis in particular." (PMID 37283755, 2023). "Similar to IL-17B, studies addressing IL-17D in psoriasis are scarce, but there is limited evidence of decreased levels in psoriatic skin lesions." (PMID 34201664, 2021). "In psoriasis, the role of IL-17B is understudied, and the scarce evidence available showed a decrease in IL17B mRNA expression in lesional skin of psoriasis patients." (PMID 34201664, 2021). "We also detected IL-17B-positive neutrophils in psoriasis plaques and cytospin slides of freshly isolated neutrophils by IHC using #AF1248." (PMID 29719541, 2018). "In B6 mice, IMQ increased expression of Il17a, Il17b, Il17c, and Il17f, partially consistent with human psoriasis, but in the BALB/c strain such genes were unaltered by IMQ." (PMID 28279190, 2017). "However, a differential role of IL-17B, IL-17C, IL-17D and IL-17E has been given during inflammation and, overall, in psoriasis." (PMID 40243580, 2025). "IL-17B has been understudied in psoriasis, but it seems to be modulated by cytokines." (PMID 40243580, 2025). "Here, for the first time, we observed that IL-17B expression increased in the mesenchymal cells in the skin dermis region, possibly upon TNF-α stimulation during psoriasis, which could subsequently trigger DCs activation and potentially other immune cells via binding to its receptor IL17-RB." (PMID 33958582, 2021). "Similarly, we show that also neutrophils isolated from patients with active psoriasis do not express IL-17F, IL-17B, IL-17C, IL-17D, and IL-17E as well as IL-17RC mRNA when activated by R848, IFNγ plus LPS, and IL-17A in vitro." (PMID 29719541, 2018).